PNPLA3 (patatin like domain 3, 1-acylglycerol-3-phosphate O-acyltransferase )
Diseases named in the same sentence as PNPLA3 in open-access papers (continued):
Sharing a sentence is not in itself a finding about the gene and the disease.
hepatocellular carcinoma (92 papers, 2010 to 2025). A malignant tumor that arises from hepatocytes. "Consistently, it has been observed in Huh-7 hepatoma cells that the overexpression of the PNPLA3 I148M variant was correlated with high levels of lactate and γ-glutamyl amino acids, a hallmark of metabolic reprogramming and mitochondrial dysfunction." (PMID 40563253, 2025). "To identify their intracellular associations, we generated a paired set of isogenic human hepatoma cells expressing PNPLA3 and PNPLA3-I148M at endogenous levels." (PMID 38657050, 2024). "Carrying the minor allele (G) rs738409 PNPLA3 mutation conferred an additive risk of hepatocellular carcinoma (HCC) (OR 2.26 [95% CI 1.23–4." (PMID 38673981, 2024). "The PNPLA3 I148M variant increases susceptibility to the whole spectrum of liver damage with progression to fibrosis up to hepatocellular carcinoma (HCC), and it is commonly considered a liver disease modifier." (PMID 37299482, 2023). "The purpose of this study was to investigate the association of PNPLA3 single nucleotide polymorphisms (SNPs) (rs738409 C > G, rs3747207 G > A, rs4823173 G > A, and rs2896019 T > G) with hepatocellular carcinoma (HCC) susceptibility." (PMID 36447249, 2022). "Variants in gene encoding for patatin-like phospholipase domain-containing 3 (PNPLA3) have been associated with an increased incidence of fat accumulation, liver inflammation and fibrosis, and hepatocellular carcinoma (HCC)." (PMID 34858322, 2021). "In the same study, PNPLA3 promoted fibrosis and the risk of developing hepatocellular carcinoma in patients with HCV." (PMID 34833371, 2021). "SNP rs738409 in the PNPLA3 gene is strongly associated with the alcoholic hepatitis, alcoholic cirrhosis, hepatocellular carcinoma (HCC) and reduced transplantation-free survival, as well as non-alcoholic fatty liver disease (NAFLD)." (PMID 31340446, 2019). "Recently, the MICA rs2596542 and DEPDC5 rs1012068 variants in Japanese individuals as well as the HCP5 rs2244546 and PNPLA3 rs738409 variants in European individuals have been found associated with hepatocellular carcinoma (HCC)." (PMID 28928439, 2017). "Recently, it has been reported that homozygosity for the 148M risk allele (henceforth PNPLA3 148M/M) also influences the risk of advanced fibrosis and hepatocellular carcinoma in CHC." (PMID 25171251, 2014). "This decision was based on our earlier study showing that PNPLA3 I148M is associated with hepatocellular carcinoma under a recessive model." (PMID 24670599, 2014). "In the present study, we employed an in vitro model of MASLD, which consisted of 3D multilineage hepatic spheroids, composed of hepatic stellate LX-2 and hepatoma HepG2 cells, homozygous for the PNPLA3 I148M sequence variant, the strongest genetic determinant of MASLD." (PMID 40608687, 2025). "Additionally, the guideline highlights that certain genetic polymorphisms, such as PNPLA-3, are also associated with a higher susceptibility to hepatocellular carcinoma (HCC)." (PMID 39230102, 2024). "One study found that loss-of-function MASLD genetic risk factors introduced into HepG2 hepatoma cells, which express endogenous PNPLA3-I148M, caused enlarged Golgi cisternae relative to parental cells, but this study did not investigate the effects of PNPLA3-I148M alone on the Golgi." (PMID 38657050, 2024). "IL-6 is known to induce hepatic inflammatory cell infiltration, while PNPLA3 represents a modifier of progression of hepatocellular injury and liver-associated disorders such as steatohepatitis, chronic hepatitis, and hepatocellular carcinoma by promoting the release of inflammatory cytokines." (PMID 33808318, 2021). "Genotype may also play a role; for example, the hepatocellular carcinoma cell line Huh7/7.5 carries the PNPLA3 rs738409 (Ile148Met) variant." (PMID 26126685, 2015).
hepatocellular carcinoma (continued). "Interestingly, the carriers of the PNPLA3 I148M variant have a substantial increased risk in cirrhosis and hepatocellular carcinoma independently of the predisposition to steatosis." (PMID 26273621, 2015). "Importantly, it has recently been reported that the I148M PNPLA3 variant is a risk factor for the development of hepatocellular carcinoma in severely obese subjects from Northern Europe." (PMID 23394097, 2013). "Here, we studied whether the PNPLA3 rs738409 polymorphism also affects predisposition to hepatocellular carcinoma (HCC)." (PMID 22087248, 2011). "Hep3B is a hepatoma cell line that expresses endogenous wild-type PNPLA3, whereas several typical human hepatoma cell lines express endogenous PNPLA3-I148M." (PMID 38657050, 2024). "To evaluate the impact of PNPLA3-I148M expression on the LD content of hepatoma cells, we performed live-cell, label-free imaging using Nanolive, a 3D holotomographic microscopic platform that allows for LD identification by their high refractive index values." (PMID 38657050, 2024). "In this study, we investigated the biogenesis of PNPLA3 and PNPLA3-I148M and the cellular consequences of constitutive endogenous I148M expression in hepatoma cells." (PMID 38657050, 2024). "We replicated the analyses in the HepaRG, a human female hepatoma cell line carrying wild-type PNPLA3 (p.148I/I genotype)." (PMID 37749332, 2023). "In this study, we aimed to investigate the niacin-I148M polymorphism crosstalk in NAFLD patients and examine niacin’s beneficial effect in reducing fat by exploiting hepatoma cells with different PNPLA3 genotype." (PMID 36937355, 2023). "Patatin-like phospholipase domain-containing protein 3 (PNPLA3) is one such gene that has not only been linked to greater risk of progressive steatohepatitis and fibrosis but also of hepatocellular carcinoma." (PMID 36458039, 2022). "The polymorphism in the patatin-like phospholipase domain-containing 3 (PNPLA3) and the transmembrane 6 superfamily member 2 (TM6SF2) genes are associated with NAFLD, NASH, fibrosis, and an increased risk of hepatocellular carcinoma." (PMID 33505944, 2021). "PNPLA3- I148M variant is strongly associated with the severity of liver disease and, likely, it is related to the progression of steatosis and progressive fibrosis, up to hepatocellular carcinoma (HCC)." (PMID 33918878, 2021). "Independent cohort studies further demonstrated that the PNPLA3 rs738409 variant confers increased risk of NASH, fibrosis, and hepatocellular carcinoma (HCC)." (PMID 33271878, 2020). "The most prominent NAFLD-associated genetic risk factor is a specific variant of PNPLA3, PNPLA3-I148M, which also predisposes for disease progression and NAFLD-associated hepatocellular carcinoma." (PMID 29286303, 2017). "Therefore, given the independent association of the PNPLA3 I148M variant with fibrosis progression and hepatocellular carcinoma risk, PNPLA3 I148M genotyping may help refining treatment prioritization to novel therapeutic regimens based on direct antiviral agents, and patients follow-up." (PMID 25171251, 2014). "Aim of this study was to evaluate whether the PNPLA3 I148M polymorphism, previously associated with hepatocellular carcinoma (HCC) risk, influences the clinical presentation of HCC and survival." (PMID 24155878, 2013). "Finally, cirrhotic carriers of the PNPLA3 variant are at increased risk of hepatocellular carcinoma (HCC), and in patients with HCC, this variant is associated with poor prognosis." (PMID 24152445, 2013). "Background and Objectives: Patients with GG rs738409 patatin-like phospholipase domain-containing protein 3 (PNPLA3) genotype (148M variant) have greater risk to develop end-stage liver disease and its associated clinical complications, including hepatocellular carcinoma (HCC)." (PMID 40731922, 2025).
hepatocellular carcinoma (continued). "The SNP rs738409 in the PNPLA3 gene, resulting in the I148M variant, is strongly associated with increased liver fat, fibrosis, cirrhosis, and hepatocellular carcinoma, independent of traditional risk factors." (PMID 40869400, 2025). "A variant of the PNPLA3 gene may be associated with MAFLD histological severity and development of hepatocellular carcinoma as well as liver-related and all-cause mortality." (PMID 40141404, 2025). "While the PNPLA3 polymorphism rs738409 C/G variant has been reliably associated with an increased prevalence of NAFLD and the progression of the disease to NASH and hepatocellular carcinoma, little is currently known about specific genes involved in NAFLD risk." (PMID 39202366, 2024). "Using paired human hepatoma cell lines expressing PNPLA3 or PNPLA3-I148M at endogenous levels, we identify the Golgi apparatus as a central node in PNPLA3-I148M-driven cellular change and characterize alterations in LD-Golgi dynamics that translate to primary human hepatocytes." (PMID 38657050, 2024). "Considering the disease-like changes induced by endogenous PNPLA3-I148M in the hepatoma cells, we asked whether endogenous expression of PNPLA3-I148M can induce similar changes in LD-Golgi dynamics in primary human hepatocytes." (PMID 38657050, 2024). "Following subsequent investigations, it has been determined that both genetic relationships are associated with clinically significant outcomes, including steatohepatitis grade, cirrhosis or hepatic fibrosis stage, and, in the case of PNPLA3, hepatocellular carcinoma in NAFLD patients." (PMID 37363524, 2023). "The single nucleotide polymorphism I148M of the lipase patatin-like phospholipase domain containing 3 (PNPLA3) is associated with an unfavorable prognosis in alcoholic and non-alcoholic steatohepatitis (ASH, NASH), with progression to liver cirrhosis and development of hepatocellular carcinoma." (PMID 36611868, 2022). "The PNPLA3 I148M variant was subsequently found to be associated with NASH, hepatic fibrosis, and hepatocellular carcinoma (HCC)." (PMID 30355853, 2018). "After matching 42 pairs remained available for a supplementary analysis: In these matched pairs of alcoholic patients with and without hepatocellular carcinoma the PNPLA3 148M allele frequencies were 53.6% vs. 31.0% (OR = 2.57; 95%-CI: 1.37–4.84; p = 0.003), respectively." (PMID 22087248, 2011). "Among these, I148M PNPLA3 variant is recognized as the most common genetic determinant of NAFLD onset and progression towards Nonalcoholic steatohepatitis (NASH) fibrosis and even hepatocellular carcinoma (HCC)." (PMID 38753115, 2024). "PNPLA3 is associated with an increased risk for NAFLD across the full spectrum of the disease including age of diagnosis, steatosis, fibrosis, and hepatocellular carcinoma (HCC)." (PMID 36684893, 2022). "In the initial studies, the PNPLA3 I148M variant was associated with intrahepatic fat content and subsequently found to be associated with NASH, hepatic fibrosis, and hepatocellular carcinoma (HCC)." (PMID 31717576, 2019). "Patatin-like phospholipase domain-containing 3 (PNPLA3) has a lipase activity against triglycerides in human and murine hepatoma cell lines." (PMID 24670599, 2014). "Two hundred and thirty-one patients with CHC were examined for PNPLA3 genotypes, liver stiffness measurements (LSM), and hepatocellular carcinoma (HCC) from May 2010 to October 2012 at Fujita Health University Hospital." (PMID 25713769, 2015). "Therefore PNPLA3-I148M, even in the absence of exogenous lipid stimulation, is sufficient to promote an effect resembling dedifferentiation of hepatocytes associated with the development of HCC, even when evaluated in hepatoma cell lines." (PMID 38657050, 2024). "Extension of PNPLA3 and TM6SF2 association has also been observed to hepatocellular carcinoma (HCC) attributable to both viral and non-viral origin, and less commonly to alcoholic liver disease." (PMID 36028802, 2022).
fibrosis (71 papers, 2012 to 2026). the formation of excess fibrous connective tissue in an organ or tissue in a reparative or reactive process. "In a study of Japanese participants, the GG genotype of PNPLA3 rs738409 was reported to cause more advanced fibrosis and liver-related diseases than the other genotypes." (PMID 40074353, 2025). "The PNPLA3 genotype is associated with major adverse liver outcomes independently of histologic fibrosis stage." (PMID 40166930, 2025). "This interpretation also reconciles our data with two recent studies reporting associations between the PNPLA3 polymorphism and steatohepatitis or fibrosis in HIV-positive patients with elevated aminotransferases and in HIV/HCV co-infection respectively." (PMID 28594920, 2017). "The present study included 231 patients, and the association between fibrosis and PNPLA3 was shown to be only a tendency by multivariable analysis, while the association was shown by multivariable analysis of the patients without past IFN treatment." (PMID 25713769, 2015). "To further characterize the specific TE cut-offs at which the SREBP1c variant is associated with fibrosis, we performed a combined sensitivity analysis of the PNPLA3 polymorphism from our previous publication and of the SREBP1c variant from the current study." (PMID 24152445, 2013). "In addition, NAFLD patients with proven GG-genotype of PNPLA3, who were at higher risk for the development of progressive disease with fibrosis, showed lower levels of circulating plasmalogens, especially 16:0, compared to those with CC- and CG-allele." (PMID 29883377, 2018). "Genetic predisposition (especially variants in PNPLA3 and TM6SF2), metabolic dysfunction, and alcohol consumption are established risk factors for steatotic liver disease (SLD) and progression of fibrosis." (PMID 41492318, 2026). "Patients with F2–F4 fibrosis had a higher frequency of PNPLA3 GG genotype than patients with F0–F1 (56.5% vs. 30.1%, p = 0.001]." (PMID 40002828, 2025). "PNPLA3 inhibition was associated with a reduced risk of NAFLD (OR: 0.08, 95% CI: 0.05 to 0.14, p=1.157 × 10−20) and fibrosis and cirrhosis of the liver (OR: 0.17, 95% CI: 0.10 to 0.30, p=2.174 × 10−9)." (PMID 40881642, 2025). "Patients with F2–F4 fibrosis had a significantly higher frequency of the PNPLA3 GG genotype than the CC + CG genotypes (44.9% vs. 21.4%, p = 0.001)." (PMID 39596570, 2024). "Among F2–F4 fibrosis, the PNPLA3 rs738409 GG genotype was significantly higher than the CC + CG genotypes (44.9% vs. 21.4%, p = 0.001)." (PMID 39596570, 2024). "The U-test also showed that PNPLA3-CG+GG, PIIINP and HA are also associated with fibrosis (z-score = 2.01, = 2.88; = 3.11; P < 0.05), while PIIINP and HA are also associated with portal inflammation (z-score = 5.8, = 5.5, P < 0.05)." (PMID 35733806, 2022). "The PNPLA3 gene variant rs738409 C>G located on chromosome 22 has been associated with susceptibility to NAFLD, development of fibrosis, increased risk of alcohol-related cirrhosis and mortality from alcoholic hepatitis." (PMID 36454904, 2022). "First, we confirmed that harboring at least one PNPLA3 G-allele was associated with a more advanced phenotype in regard to both presence of NAS ≥ 5 and advanced fibrosis on liver biopsy." (PMID 34076851, 2021). "We examined liver fat and fibrosis, genotyped for PNPLA3 gene, and assessed diet via 24-h diet recalls." (PMID 34065978, 2021). "Nevertheless, this study shows for the first time that PNPLA3 polymorphism was inversely correlated with aortic stiffness in patients with MASLD without fibrosis." (PMID 40244110, 2025). "Numerous other subsequent studies have reproduced the relationship between polymorphisms in the PNPLA3 gene and NAFLD, linking the I148M variant not only with the development of the disease but also with a greater predisposition to progression with fibrosis." (PMID 36359239, 2022). "The majority of PNPLA3-I148M mice developed severe steatohepatitis with fibrosis (p< 0.0001)." (PMID 34040583, 2021).
fibrosis (continued). "Despite the well documented variation in the prevalence of higher genotypes conveying greater risk of more advanced fibrosis with ethnicity e.g., for HSD17B13 and PNPLA3, ethnicity was not predictive of stage of fibrosis in this analysis." (PMID 37208593, 2023). "In NAFLD, the G/G genotype of PNPLA3 was associated with a higher prevalence of NASH at baseline (odds ratio [OR] 3.67, 95% CI = 1.66–8.08), but not with advanced fibrosis (OR 1.81, 95% CI = 0.79–4.14)." (PMID 36166317, 2022). "As several roles for PNPLA3 are suggested, PNPLA3 might be a good therapeutic target to control NAFLD related fibrosis and disease progression." (PMID 34025430, 2021). "It is important to note that, in our work, any patient with steatohepatitis had fibrosis in the liver histology, so we could not perform correlations between fibrosis staging and PNPLA3 liver expression." (PMID 27128907, 2016). "Fibrosis progression rate (0.27±0.41 vs. 0.20±0.26 units/year; p = 0.984) and HVPG (3.9±2.6 vs. 4.4±3.0 mmHg; p = 0.472) were similar in patients with and without PNPLA3 risk alleles." (PMID 26599080, 2015).